PELP1 (proline, glutamate and leucine rich protein 1)
Diseases named in the same sentence as PELP1 in open-access papers (continued):
Sharing a sentence is not in itself a finding about the gene and the disease.
breast carcinoma (continued). "HDAC2 can be recruited by PELP1 to miR-200a and miR-141 promoters and suppress their expression to promote EMT in breast cancer." (PMID 34993131, 2021). "More than 30 human splicing factors have now been defined, and some of them are characterized as either proto-oncogenes, such as SRSF1, SRFS3, DAM1, and PELP1, or tumor suppressors, such as RBM and PRMT6, in breast cancer." (PMID 32110852, 2020). "Pargyline-mediated inhibition of breast cancer cell growth was independently validated using the more potent KDM1 inhibitor (NCL-1) and also by using PELP1 and KDM1 siRNAs." (PMID 22812534, 2012). "To independently validate the effect of pharmacological inhibition of KDM1 on the growth of PELP1-driven (MCF-7-PELP1) and HER2-driven (MCF-7-HER2) breast cancer cells, we validated key findings using the recently developed KDM1-specific inhibitor NCL-1." (PMID 22812534, 2012). "Nongenomic ERα resides in multiprotein complexes with molecules, such as MNAR/PELP1 and src, in the cytoplasm and signals through the PI3K-Akt and MAPK pathways in breast cancer cells." (PMID 18518979, 2008). "Western blot was first performed to examine PELP1, ERα, ERβ expression in MCF-7 (ERα, ERβ positive and PELP1 highly expressed) and MDA-MB-231 (ERα, ERβ negative and PELP1 highly expressed) breast carcinoma cells as control." (PMID 34257530, 2021). "Over a third (38%) of ER coregulators identified in breast cancer are over-expressed, such as SRC3 (AIB1), SRC2, and PELP1." (PMID 28786813, 2017). "As TNBC is inherently a heterogeneous subgroup of breast cancer, we considered the possibility that further sub-division of TNBC may be necessary to fully appreciate any potential role of PELP1." (PMID 26472563, 2015). "Proline, glutamic acid, leucine rich protein 1 (PELP1) is a novel steroidal receptor co-regulator, functioning as an oncogene and its expression is maintained in estrogen receptor (ER) negative breast cancers." (PMID 26472563, 2015). "PELP1 was initially identified as a co-regulator of ERα, but its expression is also remarkably high in ERα-negative breast cancers." (PMID 26472563, 2015). "Targeting PELP1 to the cytoplasm by mutation of the nuclear localization signal (PELP-cyto) leads to activation of non-genomic signaling and Tam resistance in breast cancer cell line models." (PMID 25789479, 2015). "PELP1 has been proposed as a prognostic biomarker in hormone-related cancers, including luminal-type breast cancers, but its significance in TNBC has not been studied." (PMID 26472563, 2015). "Furthermore, ERα resides in multi-protein complexes with molecules, such as MNAR/PELP1 and src, in the cytoplasm and signals through the PI3K-Akt and MAPK pathways in breast cancer cells." (PMID 18518979, 2008). "PELP1 overexpression in ERα positive breast cancers may exceed a threshold that disrupts Rix1 complex homeostasis, resulting in dysregulated PELP1 that is not incorporated in the Rix1 complex." (PMID 36351913, 2022). "Additionally, reduction of PELP1 in ERα-negative breast cancer cell lines reduced proliferation and tumor metastasis, suggesting a role for PELP1 in tumor progression." (PMID 26472563, 2015). "However, D2 was unable to block the interaction between PELP1 and ER (data not shown) and required much higher concentrations (μM range) to block the proliferation of ER-driven MCF-7 breast cancer cells." (PMID 28786813, 2017).
breast tumors (9 papers, 2008 to 2025). "Further, previous studies have shown cytoplasmic localization of PELP1 occurs in breast tumors and contributes to endocrine resistance via Akt1 activation." (PMID 35395812, 2022). "In the case of double IHC, breast tumor cells demonstrated nuclear PELP1 expression (3,3′-diaminobenzidine; brown) and CD68 expression (Alk magenta) in the cytoplasm, indicating macrophages." (PMID 34774800, 2022). "PELP1 expression is deregulated in breast tumors, and PELP1 protein expression is an independent prognostic predictor of shorter BC‐specific survival." (PMID 33269540, 2021). "PELP1 is overexpressed in 60–80% of breast tumors and plays important roles in both ER genomic and non-genomic signaling." (PMID 26247365, 2015). "Treatment of ER-positive xenograft-based breast tumors with PELP1-siRNA-DOPC or pargyline reduced tumor volume by 58.6% and 62%, respectively." (PMID 22812534, 2012). "PELP1 is an ERα co-regulator that functions as a proto-oncogene to promote breast tumor cell proliferation." (PMID 22812534, 2012). "We found that systemic administration of PELP1 siRNA in a nanoliposomal formulation (PELP1-siRNA-DOPC) significantly reduced breast tumor growth in a xenograft model." (PMID 22812534, 2012). "PELP1 is expressed in BCa cells, and its expression is upregulated in breast tumors." (PMID 41463382, 2025). "To assess the expression of PELP1 in macrophages present in tumor milieu, we analyzed the expression of CD68, a macrophage-specific marker along with PELP1 in serial sections of inflammatory breast tumor tissues (N = 13) by double immunohistochemistry (IHC) staining and double immunofluorescence." (PMID 34774800, 2022). "Our data suggests that SETDB1-PELP1 interactions play a key role in endocrine resistance and that the PELP1 localization to the cytoplasm, commonly seen in breast tumors, may play a role in enhancing SETDB1 oncogenic signaling." (PMID 35395812, 2022). "Furthermore, patients whose breast tumors exhibit high levels of cytoplasmic PELP1 respond poorly to tamoxifen." (PMID 35395812, 2022). "Our data suggests that TFAP2C and PELP1 signaling plays a role in ER+ BC progression and that the PELP1 dysregulation, commonly seen in breast tumors, may contribute to enhanced TFAP2C oncogenic signaling." (PMID 33269540, 2021). "PELP1 has previously been shown to be overexpressed in 60–80% of breast tumors." (PMID 26247365, 2015). "Correlations between tumor PELP1 mRNA and estrogens in ER- and ER+ breast tumors." (PMID 26247365, 2015). "To examine whether PELP1-driven breast tumors can be therapeutically targeted using pargyline, we performed in vivo experiments using a postmenopausal xenograft model." (PMID 22812534, 2012). "Treatment of PELP1-driven breast tumors with pargyline reduced tumor volume by 78%." (PMID 22812534, 2012). "Finally, PELP1 correlated positively with ER mRNA (ESR1) (r = 0.553, P = 0.026) in ER+ tumors, whereas a negative association between PELP1 and ESR1 (r = -0.733, P = 0.010) was observed in ER- breast tumors." (PMID 26247365, 2015). "In the present article we target the PELP1-KDM1 axis using a nanoliposomal formulation of PELP1-siRNA-1,2-dioleoyl-sn-glycero-3-phosphatidylcholine (DOPC) administered systemically and KDM1 inhibitors in xenograft-based preclinical breast tumor models." (PMID 22812534, 2012). "The ESR1 gene is shared among 3 pathways: "PELP1 Modulation of Estrogen Receptor Activity pathway", "CARM1 and Regulation of the Estrogen Receptor pathway", and "Downregulated of MTA 3 in ER negative Breast Tumors pathway"." (PMID 18254968, 2008).
esophageal squamous cell carcinoma (9 papers, 2019 to 2025). Esophageal squamous cell carcinoma (ESCC) is a type of esophageal carcinoma (EC) that can affect any part of the esophagus, but is usually located in the upper or middle third. "Proline-, glutamic acid- and leucine-rich protein 1 (PELP1) was an oncogene, and its upregulation was linked with the progression of esophageal squamous cell carcinoma (ESCC)." (PMID 36387211, 2022). "Metformin induces GSDMD mediated pyroptosis in esophageal squamous cell carcinoma cells by targeting the miR-497/Pelp1 axis." (PMID 41562058, 2025). "PELP1 is highly expressed in esophageal squamous cell carcinoma (ESCC)." (PMID 36867378, 2023). "Moreover, PELP1 indicates a poor prognosis in patients with esophageal squamous cell carcinoma (ESCC)." (PMID 34502359, 2021). "Furthermore, PELP1 expression is correlated with poor prognosis in patients with esophageal squamous cell carcinoma (ESCC), a cancer refractory to chemotherapy." (PMID 34522213, 2021). "Metformin induces pyroptosis in esophageal squamous cell carcinoma (ESCC) by modulating the miR-49F7/PELP1 signaling axis." (PMID 41463382, 2025). "The study aimed to decipher the role of PELP1 in the progression of esophageal squamous cell carcinoma (ESCC)." (PMID 31534778, 2019).
ovarian carcinoma (9 papers, 2013 to 2025). A malignant neoplasm originating from the surface ovarian epithelium. "However, the most recent study examining PELP1 as a prognostic marker found it was associated with favorable prognosis in ERβ-positive ovarian cancer." (PMID 26472563, 2015). "To better understand the role of estrogen receptors in ovarian cancer, we evaluated them together with their coregulators—PELP1 and SRC kinase." (PMID 34207568, 2021). "Ovarian cancer xenografts models revealed that knockdown of PELP1 significantly reduced the tumor growth." (PMID 34207568, 2021). "The expression patterns of analyzed genes represent a potentially interesting target in ovarian cancer biology, especially PELP1." (PMID 34207568, 2021). "According to these findings, the prognostic relevance of PELP1 in ovarian cancer needs to be further elucidated." (PMID 23497172, 2013). "PELP1 has been described to be overexpressed in 60% of ovarian cancers and to be deregulated in several subtypes of ovarian tumors." (PMID 23497172, 2013). "The major aim of this study was to further define the role of PELP1 in human ovarian cancer and to evaluate the prognostic role of PELP1, ERalpha and ERbeta in EOC patients receiving platinum/taxane-based chemotherapy." (PMID 23497172, 2013). "Further examination of histological subtypes revealed expression of PELP1 in all included subtypes of ovarian cancer." (PMID 23497172, 2013). "In ovarian cancer cell line models and in nude mouse models elevated PELP1 expression leads to increased cell migration, metastasis and tumor progression." (PMID 23497172, 2013). "PELP1 protein level was significantly higher in control sample (ovarian cancer)." (PMID 27045366, 2016). "In human ovarian cancer tissue, only one study has focused on the role of PELP1 protein expression." (PMID 23497172, 2013). "It has been proposed, that during ovarian cancer progression, modification of PELP1 expression might occur." (PMID 23497172, 2013). "Genes related to estrogen pathways, including ESR1 and ESR2, their coregulator PELP1, and the SRC, play a role in the induction and progression of ovarian cancer." (PMID 40362695, 2025). "Further, in ovarian cancer cells, c‐Src and AKT signaling was diminished when PELP1 was downregulated." (PMID 37853941, 2024). "In this paper, we explore the expression of four estrogen signaling pathway mediators, ESR1, ESR2, PELP1 and SRC kinase in ovarian cancer patients." (PMID 34207568, 2021). "In a univariate analysis, ovarian cancer patients with PELP1 expressing tumor tissue had a better OS and DFS (p = 0.04, p = 0.004; respectively) compared to patients without PELP1 expression." (PMID 23497172, 2013). "Additionally, we investigated the correlation of estrogen-related pathway genes (ESR1, ESR2, PELP1, and c-SRC) with hsa-miR-21 and hsa-miR-145 in non-affected ovary and ovarian cancer." (PMID 40362695, 2025).
prostate carcinoma (9 papers, 2012 to 2025). A carcinoma that arises from epithelial cells of the prostate gland. "Interestingly, PELP1 has been implicated in prostate cancer due to its role in enhancing AR transcription." (PMID 40023399, 2025). "PELP-1 is also a coregulator of nuclear steroid transcription factors and is involved in cell cycle progression, playing an oncogenic role in breast and prostate cancer." (PMID 39671399, 2024). "PELP1 serves as a proto-oncogene in all hormone-responsive cancers, including breast, prostate cancers, ovarian, and other cancers." (PMID 34497633, 2021). "Research has demonstrated that PELP1 is a proto-oncogene in all hormone-responsive cancers, such as breast, ovarian, endometrial, and prostate cancers." (PMID 32117782, 2019). "The carcinogenic signaling of PELP1 is also involved in the progression of other hormone-responsive cancers including breast, endometrial, ovarian and prostate cancer." (PMID 32117782, 2019). "According to published studies, PELP1 may act as a biomarker for tumors with poor prognoses, such as breast and prostate cancer." (PMID 37853941, 2024). "Several studies have suggested PELP1 may play an important role in metastasis of tumors including breast, ovarian, endometrial and prostate cancer." (PMID 26472563, 2015). "Early studies proposed PELP1 expression as a predictor of poor outcome in patients with multiple types of carcinomas, including breast, endometrial, colorectal, and prostate cancers." (PMID 26472563, 2015). "Using Western blot analysis we showed that PELP1 is expressed in normal and ACC samples, as well as in H295R cells with a similar expression pattern to that of prostate carcinoma cell line LNCaP, which was used as a positive control." (PMID 29112114, 2017). "A recent study suggests that PELP1 mediates androgen receptor activation in the absence of androgens in PCa cells and that disruption of the complex between androgen receptor and PELP1 may be a viable therapeutic strategy in advanced prostate cancer." (PMID 22812534, 2012).
lung carcinoma (4 papers, 2014 to 2023). "Inhibiting PELP1 prevented lung cancer cells from proliferating, forming colonies, migrating, and invading." (PMID 36909198, 2023). "Gefitinib sensitivity was boosted in lung cancer cells by PELP1 inactivation." (PMID 36909198, 2023). "Dysregulation of PELP1 boosts MAPK signaling and has an impact on genes involved in cell proliferation, which aids in the proliferation of lung cancer cells." (PMID 36909198, 2023). "In addition, gefitinib’s inhibition of EGFR signaling decreased the expression of the PELP1 protein, whereas EGF’s stimulation of the EGFR pathway increased PELP1’s protein expression in lung cancer cells." (PMID 36909198, 2023).
triple-negative breast carcinoma (4 papers, 2015 to 2024). An invasive breast carcinoma which is negative for expression of estrogen receptor (ER), progesterone receptor (PR), and human epidermal growth factor receptor 2 (HER2). "Researches have confirmed that PELP1 had a diagnostic indicator for metastatic triple-negative breast cancer, and high expression of PELP1/Ki-67 in tumors was an independent prognostic factor for patients with triple-negative breast cancer (TNBC)." (PMID 32117782, 2019). "The PELP1 oncogene is commonly overexpressed in many cancers, including triple negative breast cancer (TNBC)." (PMID 35205680, 2022). "The proto-oncogene PELP1 is commonly overexpressed in many cancers including triple negative breast cancer (TNBC)." (PMID 35205680, 2022).
asthma (2 papers, 2014 to 2019). "PELP1 has also been identified as one of the potential biomarkers and may play an important role in non-cancer diseases such as asthma attacks in children." (PMID 32117782, 2019).
astrocytic tumor (2 papers, 2017 to 2019). A glial tumor of the brain or spinal cord showing astrocytic differentiation. "PELP1 may play a role in the pathogenesis and progression of astrocytic tumors and may serve as a prognostic biomarker." (PMID 32117782, 2019).
colon cancer (2 papers, 2019 to 2024). "The oncogenic signaling of PELP1 is established in several cancers, such as breast, endometrial, ovarian, salivary, prostate, lung, pancreatic, and colon cancers." (PMID 39258975, 2024). "Astonished, PELP1 can play an oncogenic role in hormone-nonresponsive cancers such as salivary, lung, pancreas, and colon cancer, although the function of estrogen receptor α and β in these cancers remained controversial." (PMID 32117782, 2019).
colorectal cancer (2 papers, 2014 to 2022). A primary or metastatic malignant neoplasm that affects the colon or rectum. "In this study, western blot and bioinformatics revealed that PELP1 expression was higher in several colorectal cancer cell lines than in immortalized normal colorectal epithelium." (PMID 24967003, 2014). "In conclusion, PELP1 exhibits an oncogenic function in colorectal cancer through c-Src upregulation." (PMID 24967003, 2014). "However, the functions of PELP1 in colorectal cancer remain unclear." (PMID 24967003, 2014). "Moreover, some researchers determined the functions of PELP1 in hormone-nonresponsive cancers, such as brain tumor, lung cancer, and colorectal cancer." (PMID 24967003, 2014).
endometrial cancer (2 papers, 2024). Primary or metastatic malignant neoplasm involving the endometrium (mucous membrane that lines the endometrial cavity). "Endometrial cancer cell survival and growth were diminished by PELP1 knockdown or by its inhibition with SMIP34." (PMID 37853941, 2024). "PELP1 inhibition with SMIP34 is a unique therapeutic approach for the management of endometrial cancer." (PMID 37853941, 2024). "Earlier studies have shown that PELP1-KD reduced cell growth, survival, and migration in endometrial cancer cells." (PMID 39258975, 2024). "The authors show that PELP1 is overexpressed in endometrial cancer." (PMID 37853941, 2024). "PELP1 has been recognized as a biomarker for cancer with negative prognoses, such as breast, prostate, ovarian, and endometrial cancers." (PMID 39258975, 2024).
gastric cancer (2 papers, 2019 to 2024). A primary or metastatic malignant neoplasm involving the stomach. "It was firstly implied antipsychotic chlorpromazine can suppress the malignant trait of gastric cancer and significantly downregulate the protein expression of PELP1." (PMID 32117782, 2019). "In this paper, it was implied PELP1 played an oncogenic role in human gastric cancer induced from in vitro cell experiment and clinical sample assay." (PMID 32117782, 2019). "The purpose of our research was to explore the biological function, clinical significance, and therapeutic targeted value of PELP1 in gastric cancer (GC)." (PMID 32117782, 2019). "In brief, PELP1 is an oncogene in human gastric cancer and the c-Src-PI3K-ERK pathway is upregulated by PELP1." (PMID 32117782, 2019). "The c‐Src‐PI3K‐ERK pathway had lower expression in gastric cancer models when PELP1 was suppressed." (PMID 37853941, 2024). "Relationship between clinicopathological characteristic and PELP1 expression in gastric cancer." (PMID 32117782, 2019). "In view of PELP1 is an oncogenic master gene, it was concluded that chlorpromazine inhibited gastric cancer through downregulation of PELP1 and PELP1 may be a molecular therapeutic target in gastric cancer." (PMID 32117782, 2019). "It was also first demonstrated PELP1 can be regarded as a therapeutic target in gastric cancer, although there is no known small molecular chemical or monoclonal antibody to target or inhibit PELP1." (PMID 32117782, 2019).
glioma (2 papers, 2022). A benign or malignant brain and spinal cord tumor that arises from glial cells (astrocytes, oligodendrocytes, ependymal cells). "In glioma, suppression of PELP1 can down-regulate the expression of VEGFA, but no further studies have been conducted, which suggests that PELP1 has a potential role in regulating tumor angiogenesis." (PMID 35053547, 2022).
hepatocellular carcinoma (2 papers, 2024). A malignant tumor that arises from hepatocytes. "An inverse relationship between PELP1 and miR-200a regulated by HDAC 2 activity and a feedback loop between HDAC 4 and miR-200a in hepatocellular carcinoma highlight the potential impact of HDAC changes on miRNA profiles, including miR-200a-3p." (PMID 38869276, 2024).